PTENP1 (phosphatase and tensin homolog pseudogene 1)
Diseases named in the same sentence as PTENP1 in open-access papers (continued):
Sharing a sentence is not in itself a finding about the gene and the disease.
cancer (75 papers, 2012 to 2025). A tumor composed of atypical neoplastic, often pleomorphic cells that invade other tissues. "Using TaqMan technology, three lncRNA PTENP1 tag single nucleotide polymorphisms (tagSNPs) (rs7853346 C>G, rs865005 C>T, and rs10971638 G>A) were genotyped in 768 GC patients and 768 cancer-free controls in a Chinese population." (PMID 28931965, 2017). "In previous studies, the mechanisms underlying the reduced PTENP1 expression in cancers were mainly divided into two categories: DNA methylation of the PTENP1 promoter and copy number alterations of PTENP1 in the genome." (PMID 28112249, 2017). "Genomic loss and down-regulation of PTENP1 is often found in aggressive human cancers, an event correlating with PTEN down-regulation through a miRNA-dependent mechanism." (PMID 24346158, 2014). "However, further studies in other cancers are needed to appraise the potential of PTENP1 in diagnostic purposes." (PMID 35655204, 2022). "It was also shown that the pseudogene PTENP1 is mutated in some cancers." (PMID 24499937, 2014). "Modifying miRNA levels to target both PTEN and PTENP1 is one of the most promising therapeutic approaches for various diseases, especially cancer." (PMID 40877546, 2025). "PTENP1 and its partners provide a complete picture of PTENP1’s endogenous regulatory roles in all cancers." (PMID 38464381, 2024). "The authors also noted the inhibition of proliferation, migration and invasion in transfected cancer cells with increased PTENP1." (PMID 38277283, 2024). "In summary, our research delves into the mechanisms of drug resistance and EMT in cancer cells, exploring the intricate interplay among PTENP1/miR-21/PTEN." (PMID 39125832, 2024). "Research highlights the importance of PTENP1 across various cancers, including prostate cancer, HCC, OSCC, and clear cell renal cell carcinoma (ccRCC) in regulating the miR-21/PTEN axis, thereby influencing EMT, drug resistance, and other cellular functions." (PMID 39125832, 2024). "This discovery adds another layer of complexity to the regulatory network involving miR-21, PTEN, and PTENP1 in cancer development and progression." (PMID 39125832, 2024). "Our work presents a comprehensive framework for investigating cellular responses following DDR, underscoring the therapeutic potential of targeting PTEN, miR-21, and PTENP1 in cancer treatment." (PMID 39125832, 2024). "A systematic review and meta-analysis of the data from the literature has recently been published revealing the prognostic value of PTENP1 expression in cancer." (PMID 37894321, 2023). "In the future, successful precision therapeutic targeting in human trials delivering miRNAs and/or PTEN and PTENP1 transcripts will have the possibility of treating various cancers." (PMID 37894321, 2023). "PTENP1 copy number loss and decreased PTENP1 expression have been reported in conjunction with PTEN loss and decreased expression in several cancer types as the result of either deletion or silencing due to promoter hypermethylation." (PMID 37894321, 2023). "Our growing knowledge of this mechanism has opened avenues for the development of strategies to alter the cellular levels of PTEN, miRNAs, and PTENP1 as a new frontier in cancer therapy." (PMID 37894321, 2023). "Alterations in the levels of PTEN, microRNAs, and PTENP1 are a new frontier in cancer therapeutics with the potential to reverse the cancer phenotype by positively manipulating the PTEN–microRNA–PTENP1 axis in favour of a precancerous cellular phenotype." (PMID 37894321, 2023). "A noteworthy finding in cancer studies pertains to PTENP1, which acts as a competitive endogenous RNA." (PMID 37834231, 2023). "PTENP1 is lost in several cancers and is known to be under selective pressure to undergo copy number loss in cancer." (PMID 37894321, 2023). "Down-regulation of these miRNAs by PTENP1 affects proliferation, migration and invasiveness of cancer cells." (PMID 35655204, 2022).
cancer (continued). "Since up-regulation of PTENP1 can also enhance the cytotoxic effects of chemotherapeutic agents on cancer cells, therapies aimed at over-expression of this lncRNA are potential ways for combating chemoresistance." (PMID 35655204, 2022). "LncRNAs like MALAT1 and HOTAIR which are associated with metastasis are over expressed in cancer and MEG3 and PTENP1 which inhibit cell proliferation and migration are downregulated in cancer." (PMID 34858475, 2021). "Low expression levels of PTENP1 are related to the cancer phenotype, and overexpression of this retro-lncRNA has been demonstrated to inhibit cancer cell proliferation." (PMID 33921034, 2021). "As has been well elucidated, a decreased level of pseudogene PTENP1 leads to inhibition of tumor suppressor PTEN in a miRNA-dependent manner in numerous cancer types." (PMID 34659409, 2021). "The underlying implication and mechanism of these promising discoveries were extended to the field of cancer when pseudogene PTENP1 was proved to share common miRNAs with its homologous coding RNA." (PMID 34659409, 2021). "These regulatory relationships between pseudogenes and genes have increasingly been explored, such as the transcriptional regulation of PTEN by pseudogene PTENP1 in several cancer conditions." (PMID 31029062, 2019). "The pseudogene, PTENP1, acts as a microRNA decoy and thus helps maintain cellular levels of PTEN, however, the PTENP1 locus is selectively lost in specific cancer cells, resulting in decreased PTEN expression and increased proliferation." (PMID 30161129, 2018). "PTEN pseudogene 1 (PTENP1) can increase PTEN expression by binding to several miRNAs to suppress proliferation of cancer cells." (PMID 30326930, 2018). "One of the major considerations in modulating PTEN/PTENP1 in cancer therapy is the majority of cancers are age related." (PMID 29455665, 2018). "Reduction in PTENP1 expression has been presented in numerous cancer studies and has been predicted to be a promising candidate as a future prognostic biomarker." (PMID 29455665, 2018). "Further to this, the oncosuppressive properties of overexpressing PTENP1 3′ UTR have been reported in various cancer cells." (PMID 26335297, 2015). "It has been shown that the pseudogene of PTEN, PTENP1, was selectively lost in some human cancer cells, resulting in decreased expression of PTEN and abnormal proliferation of cancer cells." (PMID 25502083, 2015). "One of the ceRNA most relevant to cancer spreading is PTENP1, a tumor suppressive pseudogene related to PTEN phosphatase." (PMID 24346158, 2014). "We show that methylation of the PTEN CpG island is a rare event in cancer cell lines and that apparent methylation most likely originates from homologous regions of the PTENP1 pseudogene promoter." (PMID 22490388, 2012). "Parallel to PTENP1, other pseudogenes like KRASP1 and BRAFP1 have been implicated in cancer pathogenesis through similar ceRNA mechanisms, with KRASP1 sponging miR‐143 and let‐7 family to protect KRAS mRNA and BRAFP1 enhancing oncogenic signaling by sequestering microRNAs that target BRAF." (PMID 41473691, 2025). "Manipulating PTEN, microRNA, and PTENP1 levels through therapeutic targeting represents a new frontier in cancer treatment, suggesting the potential to treat various cancer types if precise therapeutic targeting successfully surpasses the first phase of clinical trials in humans." (PMID 40877546, 2025). "Moreover, responses to PTENP1-based strategies can differ significantly between cancer types, limiting the generalizability of this approach across tumors." (PMID 40877546, 2025). "Furthermore, in studies showing lower levels of PTENP1 in cancer, it has been predicted to be a promising candidate as a future prognostic biomarker." (PMID 37894321, 2023). "Targeting PTEN and PTENP1 with microRNAs has tremendous potential in cancer therapeutics." (PMID 37894321, 2023). "The role of PTENP1 has been mostly evaluated in the pathoetiology of cancer." (PMID 35655204, 2022).
cancer (continued). "Although, in healthy adults, sexual organs appear to be the main sources of some of the most widely reported cancer-associated lncRNAs such as PVT1 and MALAT1 that are mostly expressed in the ovaries of healthy women, while PTENP1 is largely expressed in the testis of healthy men." (PMID 35729321, 2022). "Thus, PTENP1 is considered a master tumor suppressor gene, as demonstrated by the inhibition of functional conservation between different carcinomas." (PMID 35054945, 2022). "In cancer cells, down-regulation of PTENP1 expression leads to miRNA-driven degradation of PTEN." (PMID 33921034, 2021). "Since PTENP1 methylation is likely to contribute to an increase in its expression level, it can be assumed that this epigenetic modification should correlate with a more favorable prognosis for patients with cancer." (PMID 33481830, 2021). "For example, PTEN, a gene implicated in cancer, has been edited by several teams, without final sequencing of its pseudogene PTENP1 even though PTENP1 is acting as a ceRNA of PTEN." (PMID 31998363, 2019). "Researchers have shown PTENP1 to be lost or downregulated in various cancers." (PMID 31196157, 2019). "Both PTEN and PTENP1 are controlled by ceRNA circuitry in many cancers." (PMID 30326930, 2018). "Furthermore, promoter methylation leading to down‐regulation of PTENP1 expression facilitates proliferation and invasion of clear‐cell renal cell carcinoma, but up‐regulation of PTENP1 expression inhibits cancer cell survival." (PMID 27561207, 2017). "Based on online bioinformatics analysis, we predicted that PTENP1 might bind miR-193a-3p in malignant tumors." (PMID 29296207, 2017). "Studies have found PTENP1 to be lost or downregulated in various cancers." (PMID 28212532, 2017). "The processed pseudogene PTENP1 was the first ceRNA to be discovered in human cancer cells." (PMID 26442270, 2015). "Additionally, PTENP1 has been shown to regulate PTEN outside the context of cancer." (PMID 37894321, 2023). "PTENP1 is selectively lost in cancer and may regulate PTEN expression as a miRNA decoy target." (PMID 31029062, 2019). "However, many lncRNAs have been found to be differentially expressed in a variety of cancers and may act as either oncogenes, such as MALAT-1, HOTAIR, and ANRIL, or tumor suppressor genes, such as MEG3, lincRNA-p21, and PTENP1, in cancer development." (PMID 24036441, 2013). "For example, inbladder cancer, miR-107 is targeted via the long noncoding RNA RP11-79h23.3, which acts as a sponge, leading to the positive regulation of both PTEN and PTENP1." (PMID 40877546, 2025). "By integrating miR-21 knockdown with PTEN and/or PTENP1 overexpression, we aim to effectively address drug resistance and EMT, thereby significantly improving cancer therapy outcomes." (PMID 39125832, 2024). "PTENP1 activates the phosphatidylinositol-3 kinase (PI3K)/AKT pathway, and PI3K inhibitor LY294002 or siAKT prevents cancer progression." (PMID 34947885, 2021). "Here we apply state-of-the-art CRISPR technologies to study the impact that PTENP1 pseudogene transcript has on the expression levels of its parental gene PTEN, and hence on the output of AKT signaling in cancer." (PMID 32517731, 2020). "The clinical importance of PTEN inactivation in cancer and other diseases and the therapeutic potential of PTEN and PTENP1 modulation of the RKT/PI3K/Akt is discussed." (PMID 29455665, 2018). "For instance, lncRNA PTENP1, a processed pseudogene of the tumor suppressor PTEN, has been demonstrated to increase PTEN abundance and then be actively involved in cancer pathogenesis." (PMID 29803224, 2018). "In the present study, we found in 40 EEC specimens, miR-200c level was higher in most cancer areas than that in the adjacent normal endometrium, while PTEN and PTENP1 were lower." (PMID 30584245, 2018).
cancer (continued). "Multiple candidates for PTEN ceRNAs by bioinformatics prediction including PTEN pseudogene transcript PTENP1, VAPA, CONT6L, and so on, have been validated experimentally in human cancers." (PMID 27486764, 2016). "Our results demonstrated that 5 of the 6 up-regulated mRNAs in “HTLV-1 infection pathway” increased (ICAM1, WNT2B, MYC, HLA-F and TGF-β1) and 3 of the 5 down-regulated mRNAs in “Pathways in cancers” decreased (CDH1, PTENP1, HSP90AA1)." (PMID 24367666, 2013). "Nevertheless, upcoming clinical trials involving the delivery of miRNAs and/or PTEN and PTENP1 transcripts could offer more precise and effective treatment options for a wide range of PTEN-related cancers." (PMID 40877546, 2025). "Some lncRNAs (such as PTENP1, MEG3, and ZNF667-AS1) were downregulated in cancer samples." (PMID 40265013, 2025). "The expression of both genes is downregulated in different carcinomas, although PTENP1 expression is not dependent to PTEN." (PMID 35054945, 2022). "Moreover, the lncRNAs HOTAIRM1, PTENP1, and MALAT1 were found to be involved in the activation of autophagy and regulation of several physiological processes and malignant phenotype of cancer cells." (PMID 33850225, 2021). "Fer-1-like family member 4 (pseudogene) (FER1L4), cancer upregulated drug-resistant (CUDR) gene, long stress-induced noncoding transcript 5 (LSINCT-5), and phosphatase and tensin homolog pseudogene 1 (PTENP1) are the main downregulated circulating lncRNAs in GC." (PMID 34337048, 2021). "Finally, the new data presented herein further reinforces the PTENP1-PTEN paradigm and highlights the utility of CRISPR technologies for investigations of pseudogene-parental gene transcript relationships in cancer and other diseases." (PMID 32517731, 2020). "It has been found that methylation of the CpG island of PTEN is not present in many cancer cell lines but it is on the CpG island of PTENp1, which is consistent with our results." (PMID 31656200, 2019). "Previous studies have reported that PTENP1 is a pseudogene-expressed lncRNA located at 9p13.3, which competitively binds miRNAs to modulate PTEN expression by serving as a competing endogenous RNA (ceRNA) in several cancers." (PMID 30285771, 2018). "This review will discuss the regulation of oncogenic PI3K signalling by PTEN (the regulator) with a focus on the modulatory effects of the sense and antisense transcripts of PTENP1 on PTEN expression, and will further explore the potential for new therapeutic opportunities in cancer treatment." (PMID 29455665, 2018). "The mechanisms of action of PTENP1 in cancers independent of PTEN still warrant further investigation." (PMID 28112249, 2017). "PTENP1, the processed pseudogene of PTEN phosphatase, is a paradigmatic example of an oncosuppressive pseudogene that is deleted or hypermethylated in human cancer." (PMID 26442270, 2015). "Though some earlier reports suggested PTENP1 is not transcribed, more recent data suggests that the PTENP1 mRNA is ubiquitously expressed in both normal and cancer specimens." (PMID 22490388, 2012). "In addition, humans and several primates possess the PTEN pseudogene (PTENP1) that gives rise to long non-coding RNA lncPTENP1-S, which plays a pro-oncogenic role in GBM cells by upregulating the expression of cancer stem cell markers and decreasing cell adhesion." (PMID 38674599, 2024). "On the other hand, PTENP1 is another emerging cancer-related lncRNA, which can also function as ceRNA to abolish the expression of PTEN, a well-characterized tumor suppressor, thus has been considered as a cancer-promoting gene for a variety of cancers, including endometrial cancer." (PMID 35901079, 2022). "In this present study, we found that PTEN level was regulated by PTENP1 and miR-20a, whereas PTEN participated in suppressing the proliferation of cancer cells via negatively regulating the PI3K/Akt pathway, which suggested that PTEN was important in malignant transformation of cancer cells." (PMID 31196157, 2019).
cancer (continued). "In conclusion, an in-depth understanding of novel mechanisms of RTK/PI3K/Akt regulation may present new cancer therapeutic targets and opportunities through the targeting of key regulators of cell signalling downstream of RTKs, such as the PTEN/PTENP1 rheostat." (PMID 29455665, 2018). "One example is the PTENP1 and PTEN interaction, which is found only in the cancer network, but not in the normal regime." (PMID 38464381, 2024). "Taken together, PTENP1 is an important modulator of cancer progression which not only increases expression of the important tumor suppressor PTEN, but also affects expression of other cancer-related genes such as those regulating cell cycle progression." (PMID 35655204, 2022).
infection (1 paper, 2021). The state of being infected such as from the introduction of a foreign agent such as serum, vaccine, antigenic substance or organism. "The introduction of the PTENP1 shRNAs into MDA-MB-231 cells through lentiviral infection could significantly reduce PTENP1 levels with concurrently enhanced cell viability compared to the cells expressing shCont." (PMID 34065631, 2021).
PTENP1 also shares sentences with these, for which no sentence is quoted: non-small cell lung carcinoma (3 papers); acute myelocytic leukaemia (2); colorectal cancer (2); lymphoma (2); osteoporosis (2); benign renal tumors (1); chronic granulomatous disease (1); Cognitive impairment (1); colon adenocarcinoma (1); gallbladder cancer (1); Hodgkins lymphoma (1); leukemia (1); liver cirrhosis (1); lymph node metastasis (1); metastasis (1); metastatic melanoma (1); metastatic tumors (1); nevus (1); Non-Alcoholic Fatty Liver Disease (1); osteosarcoma (1); pancreatic adenocarcinoma (1); rectal tumors (1); squamous cell carcinoma (1); triple-negative breast carcinoma (1).